FOXM1 (forkhead box M1)
Diseases named in the same sentence as FOXM1 in open-access papers (continued):
Sharing a sentence is not in itself a finding about the gene and the disease.
cancer (continued). "Current knowledge of FOXM1 isoform expression in different cancer types is inconsistent and has not been defined in relation to normal tissues or paired normal and tumor samples." (PMID 30795624, 2019). "Additionally, we observed a highly significant correlation between FOXM1 and CCNE1 mRNA and Cyclin E1 protein expressions in TCGA pan-cancer and HGSC primary tumor data." (PMID 30795624, 2019). "A novel FOXM1 isoform has been identified more recently: FOXM1D; FOXM1D has an essential function in Rho/ROCK activation, a signalling pathway involved in actin cytoskeleton organisation and cancer invasion." (PMID 30621735, 2019). "Nonetheless, the mechanism by which FOXM1 mediates its oncogenic effects in these cancers is not well-understood." (PMID 31390744, 2019). "While FOXM1 over-expression is reported in many different cancers, there has not been a comprehensive pan-cancer analysis of FOXM1 status." (PMID 30795624, 2019). "This inhibitor restored cancer cell growth, invasion, and migration in HGK-treated cells (especially Huh7 cells), indicating that the anticancer mechanism of HGK is mediated through miR-320a downregulation of FOXM1." (PMID 31877715, 2019). "Key findings from our studies have identified E2F1, FOXM1, and ETS1 as coding gene/s axes that are overexpressed and may show strong involvement in tumor development in almost all cancer types." (PMID 30809433, 2019). "FOXM1 is located at 12p13.33; 12p gains are pathognomonic for TGCT, and isochromosome 12p gains occur in 87% of TGCT, likely accounting for increased FOXM1 expression in this cancer type." (PMID 30795624, 2019). "In contrast, proteins that promote various cancer malignant properties, including CCND1, ERBB2, SNAIL, SLUG, phosphorylated STAT3 (p-STAT3), FAK, FOXM1, ETS1, YAP, HES1, and OCT4, were all significantly downregulated, an indication of reduction of malignancy in the cancer cells after EZH2 knockdown." (PMID 31130994, 2019). "Cyclin D1/Cdk4 activates FOXM1 by releasing its TAD from repression by RB, which might lead to deregulated proliferation and cancer." (PMID 30208972, 2018). "Despite these findings, no drugs targeting FoxM1 are available in clinical use for cancer therapy so far." (PMID 29765517, 2018). "Current anti-cancer drugs, including paclitaxel, doxorubicin, epirubicin, lapatinib, gefitibin, imatinib and cisplatin, have been confirmed to mediating their cytotoxic and cytostatic functions through FOXO3 and FOXM1." (PMID 29180117, 2018). "However, among the 96 samples of undifferentiated type (undifferentiatied carcinoma, UDC), high expression of FoxM1 was found in 54 cases." (PMID 30416986, 2018). "We found that FoxM1 protein was weakly expressed in differentiated type of NPC (differentiated nonkeratinizing carcinoma, DNKC)." (PMID 30416986, 2018). "While other researches demonstrated that doxycycline could inhibit the progression of cancer stem cell phenotype and EMT through FOXM1 and IκB/NF-κB signal pathway." (PMID 29285218, 2017). "Our current study investigated lncRNA, miRNA, and protein-coding genes and found that MALAT1, miR-320a, and FOXM1 could form a gene signaling pathway to regulate HUVEC proliferation, which may provide a novel strategy for future control of cancer progression." (PMID 28977880, 2017). "For example, in the seven cancer types (BLCA, ESCA, HNSC, KIRC, LIHC, STAD and UCEC) with both grade phenotype information and normal control samples, expression of AURKB, BUB1, FOXM1, HMMR, MYBL2, and PLK1 follows the pattern in five cancer types (BLCA, HNSC, KIRC, LIHC, and UCEC)." (PMID 28427185, 2017). "FOXM1 is a transcription factor driving the FOXO-dependent genes in regulation of cancer cell cycle progression and proliferation as well as in promotion of angiogenesis, EMT signalling, and cancer cell migration and invasion." (PMID 28740192, 2017).
cancer (continued). "FOXM1 and B-MYB are overexpressed in a wide range of different cancers." (PMID 28061449, 2017). "Forkhead Box M1 (FOXM1), a transcription factor of the forkhead family, is well demonstrated to be critical for proliferation, apoptosis, migration and invasion of human cancer." (PMID 28427178, 2017). "However, when SMYD2 is transactivated in cancer cells, stabilized β-catenin is methylated by SMYD2, binds to FOXM1, enters into the nucleus with FOXM1, and then activates downstream genes in the Wnt/β-catenin/TCF pathway." (PMID 28915556, 2017). "We identified consistently upregulated genes (such as E2F1, EZH2, FOXM1, MYBL2, PLK1, TTK, AURKA/B and BUB1) and consistently downregulated genes (such as SCARA5, MYOM1, NKAPL, PEG3, USP2, SLC5A7 and HMGCLL1) across various cancers." (PMID 28427185, 2017). "Despite the unexpected findings of invasion assay, we assessed by RT-qPCR that some FOXM1 downstream targets involved in metastasis, cancer progression, and cisplatin resistance, such as MMP2 and MACC1, were specifically down-regulated in OSPC2 cells after FOXM1 silencing." (PMID 28482906, 2017). "Our data, showing that CDK6 phosphorylates and thereby stabilizes FOXO3, are highly reminiscent of the effects elicited on FOXM1, a related transcription factor, that, following phosphorylation by CDK4 and CDK6, is stabilized and transactivated to prevent senescence of cancer cells." (PMID 28778953, 2017). "FOXM1 protein expression was strongly expressed in several cancer tissues (patient No. 9, 19, 20), whereas low expression was observed in normal tissues using a tissue microarray." (PMID 28902136, 2017). "The survival analysis shows that individuals with tumors expressing low levels of FOXM1 had a significant survival advantage when compared with individuals with tumors expressing high levels of FOXM1, not only in GBM patients but also in other cancer histologies." (PMID 27764801, 2016). "Furthermore, inhibition of LDHA activity diminished the enhanced glucose consumption and lactate production effects of FOXM1 overexpression, while in vivo studies established that upregulation of FOXM1 promoted LDHA expression, cancer growth and metastasis." (PMID 26269128, 2016). "Together, FOXM1 and CENPF regulate target gene expression and activation in cancer cells." (PMID 27072587, 2016). "Since GLUT1 and HK2 are critical enzymes involved in reprogramming of glucose metabolism in cancer cells, we next sought to determine whether GLUT1 and HK2 are directly regulated by FOXM1 in EOC cells." (PMID 27351131, 2016). "Moreover, MELK expression levels were strongly correlated with those of forkhead box protein M1 (FOXM1) known as an important transcriptional factor and a master regulator of mitosis in cancer stem cells." (PMID 26933922, 2016). "FOXM1 is overexpressed in many types of cancer and is usually absent in terminally differentiated cells." (PMID 27074562, 2016). "Such co-regulation in cancer samples has not previously been investigated; as studies have been limited to studying either FOXM1 or PLK1 expression in these tumours." (PMID 26576650, 2015).
cancer (continued). "To address this issue, we have extended these studies to a broader cohort of FOXM1 target genes, the majority of which are novel targets and have not previously been studied in the context of cancer." (PMID 25889361, 2015). "First, we asked whether FOXM1 expression was higher in the OAC-derived samples, and we found it to be expressed to significantly higher levels across cancer samples." (PMID 25889361, 2015). "FOXM1 overexpression has been observed in a variety of different tumour types and our recent work indicated that in the context of OAC, several of its target genes, including PLK1, are co-ordinately overexpressed in this cancer type." (PMID 25889361, 2015). "Since SUMOylation of FOXM1B is essential for FOXM1B transcriptional activity, targeting SUMOylation at K463 of FOXM1B provides a suitable therapeutic intervention in addition to the existing FOXM1-based cancer therapies." (PMID 24918286, 2014). "Although not reaching statistical significance, FOXM1 overexpression displayed a trend related to serous histological type (P = 0.142), high grade cancers (poor differentiation) (P = 0.235) and chemoresistance (P = 0.282)." (PMID 25411964, 2014). "Considering the critical role of FOXM1 in promoting mitosis, it is not surprising that the level of this protein is upregulated in various human cancers." (PMID 23386997, 2013). "Unlike in cancer progression we show that an increase in Cav-1 and Vegf expression is negatively correlated with Foxm1 expression." (PMID 24391823, 2013). "Although all of these aberrantly activated factors are dominantly associated with cancer pathogenesis, there is no report so far to mention the signaling link amongst GRB7, ERK activity and FOXM1 in human cancer cells." (PMID 23285101, 2012). "In that regard, overexpression of FoxM1 was shown to specifically override bortezomib-induced-apoptosis, but not doxorubicin-induced cancer cell apoptosis." (PMID 20339519, 2009). "UBE2S, HIF‐1α, and FOXM1 may play a role in the progression of esophageal HIN and LIN to cancer." (PMID 41427004, 2025). "The role of FOXM1 is limited to driving the migration and invasion of cancer cells to distant organs, and its expression may not be significantly expressed or reflected in liver metastases." (PMID 40806530, 2025). "Notably, FOXM1 plays a critical role in treatment resistance, particularly against HER2-targeted therapies such as trastuzumab and lapatinib, where elevated FOXM1 levels enable cancer cells to evade therapeutic effects." (PMID 40002266, 2025). "Other cancer antigens, while exhibiting downregulated expression in liver tissue compared to primary tumors, may not exhibit as marked a decline as FOXM1 and SPARC, underscoring their distinct biological roles in tumor progression and metastasis." (PMID 40806530, 2025). "Importantly, treating cancer cell lines with various thiazole antibiotics, such as Thio, specifically blocks FoxM1 transcriptional activity and expression without affecting the general transcriptional profile of the cancer cells." (PMID 40628925, 2025). "Moreover, FOXM1 expression was elevated uniquely in cancers but not in Barrett’s esophageal samples, suggesting that its overexpression is cancer-specific rather than metaplasia-induced." (PMID 38373993, 2024). "Notably, STL001 does not provide further sensitization to FOXM1-KD cancer cells, suggesting that the sensitization effect is conveyed specifically through FOXM1 suppression." (PMID 38697979, 2024). "Importantly, FOXM1 and FOXO expressions are also inversely correlated in cancers." (PMID 37686402, 2023). "In addition, the overexpression of FOXM1 in MCF7 or Hela cells with relatively low endogenous levels of FOXM1 resulted in heightened sensitivity towards M1-20, supporting that M1-20’s anti-cancer efficacy correlated with the FOXM1 levels in cancer cells." (PMID 37598210, 2023). "Unlike in cancer cells, FOXM1 is known to have the opposite effect in chondrocytes." (PMID 37908734, 2023).
cancer (continued). "The presence of FOXM1 Apt as a therapeutic aptamer and Dox as a chemotherapeutic drug together in the design of the delivery platform increases the efficiency of cancer therapy and decreases toxicity for nontarget cells compared to free drugs by decreasing the required amount of Dox." (PMID 37736517, 2023). "Meanwhile, FOXM1-PROTAC decreased the cancer cells glucose metabolism via downregulating the protein expression levels of glucose transporter GLUT1 and the immune checkpoint PD-L1, which suggests involvement of FOXM1 in cancer cell metabolism and immune regulation." (PMID 36171633, 2022). "Inactivation of FOXM1, an important protein in cancer development and chemoresistance, as part of a FOXM1-AKT-positive regulation circuit, effectively sensitizes venetoclax-resistant AML cells, also making FOXM1 an interesting therapeutic target to combine with targeting BCL-2." (PMID 35884517, 2022). "Since PDK1 is a critical enzyme that regulates glycolytic metabolism in cancer cells and our results have demonstrated that PDK1 is regulated by FOXM1, we next sought to determine whether PDK1 is involved in the elevated glycolysis and cell proliferation rates regulated by FOXM1." (PMID 35656815, 2022). "Previous study has suggested the proto-oncogenic roles of FOXM1 and its downstream target genes Cyclin D1, Survivin and CDC25B in tumors, which include facilitating cell cycle progression and inducing tumor cell proliferation, as well as its relation with the poor prognosis of cancer patients." (PMID 35624501, 2022). "Interestingly, Hippo pathway deregulation in cancer has been shown to drive FOXM1 activation through YAP–TEAD-dependent FOXM1 transcription, while FOXM1 additionally interacts directly with TEAD on target gene promoters, contributing to cell proliferation and tumor development." (PMID 33445626, 2021). "Indeed, studies aimed at FOXM1 inhibition in cancer cells have observed a decrease in cell proliferation and migration, metastasis, angiogenesis, EMT, and drug resistance, demonstrating the implication of FOXM1 in these different processes." (PMID 33953844, 2021). "On the other hand, FoxM1 positively promotes ATP binding cassette subfamily a member 2 (ABCA2) expression but is also regulated by the FoxM1/PHB1/RAF‐MEK‐ERK feedback loop, which may induce additional resistance of cancer cells to Taxol." (PMID 34766149, 2021). "Overall, these results suggest that FOXM1 is predicted to function as a master regulator of the cell cycle through the interaction of NFY-family proteins, and therefore the inhibition of FOXM1 could be an attractive strategy for cancer therapy." (PMID 32858881, 2020). "FOXO3 and FOXM1 exert opposing functions in the regulation of cancer-related processes, and targeting the FOXO3-FOXM1 axis could be a viable strategy for the treatment of cancer." (PMID 31450545, 2019). "Thus, the observed increase in overall FOXM1 expression in cancer is not due to differential expression of any particular isoform." (PMID 30795624, 2019). "Furthermore, although MELK has been suggested to form a heterotrimeric protein complex with the oncogenic transcription factors c-Jun and FoxM1 in cancer stem cells, MELK lacks the binding ability in normal progenitor and stem cells." (PMID 29416794, 2018). "This review will focus on the role and regulation of FOXO3 and its key downstream target FOXM1, and discuss their central roles as modulators of fundamental cellular processes with special emphasis on our understanding of the current therapeutic potential of targeting the FOXO3-FOXM1 axis in cancer." (PMID 29180117, 2018).
cancer (continued). "Given the oncogenic role of MALAT1 in human cancers, MALAT1 could mediate HUVECs proliferation in human carcinogenesis and cancer progression; thus, targeting of the MALAT1-miR-320a-FOXM1 signaling could serve as a novel strategy for therapeutic intervention in HUVECs-driven angiogenesis." (PMID 28977880, 2017). "Several studies show that the transcription factor Forkhead box M1 (FOXM1) is widely expressed in solid tumors, acting as a principal promoter of cell-cycle progression, response to DNA damage and drug resistance, where its overexpression confers proliferative advantages to cancer cells." (PMID 28482906, 2017). "The transfection of M-FOXM1 Apt resulted in a dramatic inhibition of cell proliferation and down-regulation of the expression of FOXM1 target genes without changing the levels of FOXM1 mRNA and protein in cancer cells." (PMID 28358012, 2017). "Additional studies using immortalized MEFs demonstrated that FOXM1 expression is induced by oncogenic stresses requiring ROS and that up-regulated FOXM1 engages a negative feedback loop to counteract ROS increases and protect dividing and cancer cells from oxidative stress." (PMID 27385468, 2016). "Given the importance of GLUT1 and HK2 in reprogramming of glucose metabolism in cancer cells, we hypothesized that aberrant expression of FOXM1 in EOC cells could also promote reprogramming of glucose metabolism, one of the hallmarks of cancer, to facilitate cancer proliferation." (PMID 27351131, 2016). "Forkhead box M1 (FOXM1) and FOXO3a have been observed to compete in binding to similar DNA sequences, which often results in antagonized transcriptional output that has recently been related to genotoxic drug resistance and the response of various cancers to chemotherapy." (PMID 27284014, 2016). "As a consequence, the induction of abnormal spindle formation through FOXM1 and its downstream target KIF20A, may represent a novel strategy for overriding taxane resistance as well as for cancer treatment, as ensuing aberrant mitosis will culminate in senescence and/or cell death." (PMID 25961928, 2016). "The Forkhead box M1 (FOXM1) transcription factor has a pivotal role in promoting cell proliferation, migration, invasion, angiogenesis, stem cell renewal and DNA damage repair, thus influencing cancer initiation, progression, metastasis, angiogenesis and drug sensitivity." (PMID 27526106, 2016). "As shown in recent studies, targeting FoxM1 signaling by novel small interference RNA silencing technique or miR-200 family members would be useful for reversing the EMT phenotype, which would likely result in the reversal of drug resistance and elimination of cancer cells." (PMID 25935853, 2015). "Therefore FoxM1 might up-regulate the expression of MMPs and VEGF, EMT to increase the capacity of cancer invasion and influence embryo implantation." (PMID 25522167, 2014). "It is therefore not surprising that deregulation of FOXM1 could result in severe pathological conditions, including cancer." (PMID 25411964, 2014). "FOXM1 is without a doubt emerging as a critical regulator of cancer development that may affect all hallmarks of cancer." (PMID 23761863, 2013). "First, it is not clear whether the MELK/FOXM1 protein complex plays a positive role in cancers or cancer stem cells in other organs." (PMID 23404835, 2013). "In the attempt to identify pre-cancer or predictive cancer biomarkers accrued during aberrant cell proliferation induced by FOXM1, we have investigated this using genome-wide methylome arrays to identify FOXM1-orchestrated differentially methylated genes in primary normal human epithelial cells." (PMID 23087907, 2012).